MYC (MYC proto-oncogene, bHLH transcription factor)
Diseases named in the same sentence as MYC in open-access papers (continued):
Sharing a sentence is not in itself a finding about the gene and the disease.
COVID-19 (18 papers, 2021 to 2024). A disease caused by infection with severe acute respiratory syndrome coronavirus 2. "In accordance with the PPI analyses, we found that the V-ATPase subunit ATP6V1B2, the c-MYC co-activator TRRAP, and the cohesin complex subunit SMC3 were associated with the COVID-19 patient hospitalization, suggesting their clinical relevance to disease." (PMID 38168026, 2024). "In silico analysis of deregulated lncRNA in SARS-CoV-2, infected cells or tissues from COVID-19 patients provided comprehensive information of their target genes/proteins and mechanism of deregulation lncRNAs by IRFs, STATs, MYC, and RelA/p65." (PMID 34940755, 2021). "This information suggesting that targeting MYC for COVID-19 or CoV mediated respiratory disease has a potential role in the SARS-CoV-2 pathogenesis." (PMID 33968364, 2021). "Consistently, we found upregulation of pathways associated with tissue damage in COVID-19, including Reactive Oxygen Species (ROS) pathway, EF2 targets, G2M checkpoint, mitotic spindle, and MYC targets, in lung samples from mice receiving vehicle, both at 4 and 7 days post-infection (Fig. EV5F)." (PMID 39009832, 2024). "CD8+ T cell proliferation can be expected in the lungs of COVID-19 patients, and a significantly higher (89%) average MYC expression was indeed found in the active infection group compared with the control in this data set (P < 0.0032, unpaired Wilcoxon test), supporting SiPSiC's higher robustness." (PMID 38981682, 2024). "Furthermore, MYC is another target gene of COVID-19, has been reported to have various functions, including regulation of chromatin sites, modulation of cellular metabolism, and versatility across various cell types." (PMID 36913345, 2023). "Analysis of SARS-CoV-2 infected lung transcriptomics data identifies miRNAs that could target MYC indicating a possible role of MYC in the pathogenesis of COVID-19." (PMID 34940755, 2021). "Our analysis demonstrates decreased expression of several MYC and MAX targets in patients with severe COVID-19." (PMID 38262689, 2024). "MiR-21-5p and miR-22-3p, both upregulated in COVID-19 patients, target several genes involved in cell signaling, cell proliferation and angiogenesis (e.g., HIF1A, MYC, SP1, SMAD7, VHL)." (PMID 36032130, 2022). "During COVID-19, miR-21-5p may directly target CCL20, which is up-regulated in the inflamed airway epithelium, as well as MYC, the over-expression of which fosters the inflammatory response and T-cell metabolic reprogramming, respectively." (PMID 36142450, 2022). "Lastly, from the second set, MYC is associated with alternative macrophage activation, secreting anti-inflammatory cytokine in moderate patients, which may help balance the damage held by the pro-inflammatory cytokines; this function is not present in COVID-19 patients." (PMID 34603282, 2021).
lung squamous cell carcinoma (18 papers, 1998 to 2025). "It was also reported that MYC could enhance the oncogenic effect of FGFR1 in squamous cell lung cancer." (PMID 31695781, 2019). "Pharmacological ubiquitin-specific protease 28 (USP28) inhibition reduces c-MYC, c-JUN, and Δp63 protein levels in mouse lung squamous cell carcinoma (LSCC) tumours and induces tumour cell death." (PMID 34636321, 2021). "Pharmacological inhibition of ubiquitin-specific protease 28 (USP28) prevents human lung squamous cell carcinoma (LSCC) tumour progression and reduces c-MYC protein levels in xenograft models." (PMID 34636321, 2021). "For example, an L-M-FFL motif comprised of KB-1732A1.1, MYC, miR-93, and CCND1 was only dysregulated in lung squamous cell carcinomas, and an L-M-FFL motif including LINC00662, MYC, miR-34a and VEGF was only dysregulated in kidney cancer." (PMID 27322142, 2016). "For this reason, immunohistochemistry was used to examine the squamous cell lung carcinomas from 121 patients for their expression of ERBB-1, vascular endothelial growth factor (VEGF), cyclin A, FOS, JUN and MYC." (PMID 9484827, 1998). "MYC, JUN, and Δp63 are highly expressed in lung squamous cell carcinoma (LSCC) tumours." (PMID 34636321, 2021).
myelodysplastic syndrome (18 papers, 2008 to 2025). A clonal hematopoietic disorder characterized by dysplasia and ineffective hematopoiesis in one or more of the hematopoietic cell lines. "Although no MYC-targeting compounds have yet entered clinical trials, APTO-253, which partially reduces MYC expression, is currently undergoing phase I trials for relapsed or refractory AML or myelodysplastic syndromes (NCT02267863)." (PMID 40781078, 2025). "Since MYC is frequently amplified and/or overexpressed in human AML (13%) and in MDS which may develop AML later and was previously called as preleukemia, we constructed an Myc-induced murine AML model." (PMID 37130348, 2023). "Several published literatures revealed that some oncogenes, such as MYC and MLL, have been identified to be amplified on dmins in AML and myelodysplastic syndrome (MDS)." (PMID 34194582, 2021).
plasma cell neoplasm (18 papers, 2005 to 2025). A clonal proliferation of immunoglobulin-secreting plasma cells. "Given that MYC dysregulation is a hallmark of plasma cell neoplasms, CDCA7L emerges as a strong candidate for the functional basis of the rs4487645 association." (PMID 40244254, 2025). "In plasma cell neoplasms MYC has been associated to disease progression from MGUS to MM and to a shorter survival of MM patients." (PMID 38732105, 2024). "However, given the infrequent occurrence of IgH class switch recombination in plasma cell tumors and the association of complex MYC gene translocations and insertions with advanced disease stages, MYC rearrangement is considered a potential mechanism underlying genomic instability." (PMID 39664374, 2024). "The fact that Vk*MYC mice develop plasma cell tumors with spontaneous aberrant activation of APOBEC further support the similarities in the molecular pathogenesis of disease progression between VK*MYC and human MM." (PMID 38714690, 2024). "Vk*MYC mice under glyphosate exposure developed progressive hematological abnormalities and plasma cell neoplasms such as splenomegaly, anemia, and high serum IgG." (PMID 31277689, 2019). "Myc-induced lymphoblastic B-cell lymphoma (LBL) in iMycEμ mice may provide a model system for the study of the mechanism by which human MYC facilitates the initiation and progression of B cell and plasma cell neoplasms in human beings." (PMID 16277667, 2005). "Early induction studies with retroviral vectors clearly showed that overexpression of MYC alone could not induce PCTs; but when MYC was paired with RAS or RAF, high incidences of plasma cell tumors could be induced even in PCT-resistant strains of mice." (PMID 32923678, 2020). "Notably, unlike plasma cell neoplasms, PBL often exhibits MYC overexpression." (PMID 39944461, 2025).
teratoma (18 papers, 2011 to 2024). A non-seminomatous germ cell tumor characterized by the presence of various tissues which correspond to the different germinal layers (endoderm, mesoderm, and ectoderm). "In addition, these models utilize transduction of fibroblast with retroviruses encoding OCT4, SOX2, KLF4 and c-MYC, which are by and large cancerous and form teratomas." (PMID 25140287, 2014). "We also confirmed that all the patient-derived iPSC lines expressed the embryonic stem cell markers OCT3/4, SOX2, NANOG, REX1, MYC, and KLF4 and were capable of forming teratomas." (PMID 29088246, 2017).
brain cancer (17 papers, 2016 to 2025). A primary or metastatic malignant neoplasm affecting the brain. "The tumor masses also express high levels of MYC oncoprotein, which is known to play an important role both in CNS development and numerous types of tumors, including brain cancers." (PMID 40507925, 2025). "The overexpression of MYC genes is frequently found in many human cancers, including adult and pediatric malignant brain tumors." (PMID 39538178, 2024). "An elevated level of DEPTOR can be observed in breast, lung and brain cancer cells with MYC overexpression, while a concomitant decrease in DEPTOR expression was found in MYC depleting cells or in cells treated with BET inhibitors." (PMID 29472861, 2018). "This review focuses on the role of MYC proteins and their regulatory network in malignant brain tumors." (PMID 28333115, 2017). "In addition, we and others have identified MYC as a target of different pathways in recent studies on brain cancer carried out in the fly, so we investigated its expression in the presented model." (PMID 40507925, 2025). "If we are to determine how increased MYC might contribute to brain cancer progression, we will require a more complete understanding of MYC’s roles during normal brain development." (PMID 33092025, 2020). "Although members of the MYC family are upregulated in nervous system tumours, the mechanisms of how elevated MYC promotes stem cell-driven brain cancers is unknown." (PMID 33092025, 2020). "We then investigated the efficacy of ixabepilone in the treatment of MYC-amplified PDX established as intracranial tumours in mice, previously demonstrated as the gold standard in the field of brain cancer modelling." (PMID 34154646, 2021). "MYC family proteins (c-MYC, MYCN, and MYCL) are misregulated in various malignant brain tumors in children and adults." (PMID 28333115, 2017). "It is not clear how well many direct MYC inhibitors or MYC-MAX interaction inhibitors penetrate the BBB/BTB and if they will provide efficacy in malignant brain tumors." (PMID 33585252, 2020).
esophageal adenocarcinoma (17 papers, 2008 to 2025). A malignant tumor with glandular differentiation arising predominantly from Barrett mucosa in the lower third of the esophagus. "The expression of CIP2A and c-MYC were associated with one another, and in most cases of esophageal adenocarcinoma they were found to be co-overexpressed." (PMID 25015035, 2014). "While c-MYC expression has been widely characterised in oesophageal adenocarcinoma, expression of members of the MAD family of putative c-MYC antagonists is yet to be studied in any detail in gastrointestinal carcinogenesis." (PMID 18493233, 2008). "To conclude, the overexpression of c-MYC in Barrett's metaplasia and oesophageal adenocarcinoma has been confirmed." (PMID 18493233, 2008). "Elevated expression of c-MYC has been demonstrated in oesophageal adenocarcinoma; however, the expression of other members of the MYC/MAX/MAD network has not been addressed." (PMID 18493233, 2008). "Quantitative real-time RT–PCR was utilised to assess the expression of the mRNAs encoding c-MYC, MAD1, MXI1, MXI1-0 and MAX in normal epithelia, Barrett's metaplasia and oesophageal adenocarcinoma specimens." (PMID 18493233, 2008). "Furthermore, outside the nervous system, both are involved in a variety of cancers with recent evidence linking them to esophageal adenocarcinoma and c-MYC-dependent control of cell proliferation." (PMID 38289221, 2024). "Consistent with previous work expression of c-MYC was deregulated in oesophageal adenocarcinoma." (PMID 18493233, 2008). "We hypothesised that MAD expression would be repressed in the progression of oesophageal adenocarcinoma in a reciprocal pattern to c-MYC." (PMID 18493233, 2008). "One study focusing solely on esophageal adenocarcinomas showed that the chemoresistance was conveyed through alteration of the Wnt/β-catenin pathway and DKK2, CDH1, CD44, MYC, and ABCG2 expression." (PMID 31467538, 2019). "Immunohistochemical staining was utilised to establish MYC/MAX/MAD network protein localisation in normal oesophageal and gastric epithelia, Barrett's metaplasia, dysplastic Barrett's epithelium and oesophageal adenocarcinoma." (PMID 18493233, 2008). "In accordance with the mRNA data c-MYC, MAD1 and MXI1 expression was significantly higher in oesophageal adenocarcinoma than in matched normal gastric controls." (PMID 18493233, 2008). "Research focused on Barrett’s esophagus and esophageal adenocarcinoma have also suggested that BIRC2, BIRC3, MMP12, MYC, PVT1, and YAP1 may be ecDNA-related oncogenes." (PMID 40569942, 2025). "Exposure of Barrett’s and esophageal adenocarcinoma cells to acidic bile salts activated EGFR-Stat3 signaling (EGFR-STAT3 protein complex) and induced the expression of Stat3 target genes (IL-6, IL-17A, BCL-xL, Survivin, and c-MYC)." (PMID 34884765, 2021). "Our findings show that MYC is downregulated with shCDK9 in esophageal adenocarcinoma while MYC downregulation by the CDK9 inhibitors is not consistent across three esophageal adenocarcinoma cell lines." (PMID 28404924, 2017). "The expression of c-MYC in human oesophageal malignancy has previously been documented, demonstrating that c-MYC expression is elevated in Barrett's metaplasia and further overexpressed in oesophageal adenocarcinoma." (PMID 18493233, 2008).
heart failure (17 papers, 2017 to 2025). Inability of the heart to pump blood at an adequate rate to meet tissue metabolic requirements. "This inconsistency further emphasizes the complexity of the MYC-regulated transcriptional network and heart failure progression." (PMID 37234159, 2023). "The up-regulation of c-MYC has been shown to be a central component in the Wnt/β-catenin/c-MYC axis mediated cardiac remodeling abnormalities in heart failure." (PMID 33706714, 2021). "The functions of other MYC and C/EBPβ target genes should be further studied to reveal their connections with heart failure." (PMID 32460775, 2020). "Nevertheless, our analysis suggests that transcription factor MYC and C/EBPβ play critical roles in heart failure developmental progress." (PMID 32460775, 2020). "A Link between TCF7L2, WNT/β-catenin and MYC pathways has been described during cardiac remodeling in heart failure or in the context of pancreatic beta cell proliferation." (PMID 32517078, 2020). "The inconsistence further emphases the complex transcriptional network regulated by MYC and the complex developmental progress of heart failure." (PMID 32460775, 2020). "Our results suggested that metabolism pathways and insulin signaling pathway, transcription factors MYC and C/EBPβ played critical roles in heart failure developmental progress." (PMID 32460775, 2020). "By comparative analysis, our results provide the changed expression profiling of metabolism signaling pathway, insulin signaling pathway, transcription factors MYC and C/EBPβ in the development of heart failure." (PMID 32460775, 2020). "All those results highlighted the importance of MYC, C/EBPβ and their downstream target genes in heart failure development." (PMID 32460775, 2020). "We also tried to determine the MYC and C/EBPβ mediated downstream target genes and construct the complex transcriptional networks regulated by MYC and C/EBPβ in heart failure developmental progress." (PMID 32460775, 2020). "Metabolism signaling pathway, insulin signaling pathway, transcription factors MYC and C/EBPβ were inhibited in heart failure developmental progress." (PMID 32460775, 2020). "All these results suggest a potentially important role of MYC in heart failure." (PMID 37234159, 2023). "MYC’s role in regulating heart failure development is quite complex." (PMID 37234159, 2023). "Furthermore, the precise mechanisms of MYC and C/EBPβ in heart failure development require further elucidation by MYC and C/EBPβ knockout mouse." (PMID 32460775, 2020). "At last, we constructed MYC and C/EBPβ mediated regulatory networks in failing heart tissues, and identified the MYC and C/EBPβ target genes which had been reported involving the heart failure developmental progress." (PMID 32460775, 2020). "All those results emphasized the important roles of MYC and C/EBPβ in heart failure development." (PMID 32460775, 2020). "Furthermore, through literature research, we found that some MYC target genes were previously reported involving the development of heart failure, including STAT3, PRMT1, PRKCH and HSPA4." (PMID 32460775, 2020). "All those results suggest the potentially significant roles of MYC in heart failure." (PMID 32460775, 2020). "The functions of MYC in the regulating of heart failure development are rather complicated." (PMID 32460775, 2020). "Therefore, we can speculate that up-regulation of MYC may increase macrophage aggregation in heart failure myocardium." (PMID 37234159, 2023). "However, the functions of MYC in the development of heart failure are unclear." (PMID 32460775, 2020). "It has been previously demonstrated that MYC, MAP2K1, and STAT3 all have a critical role in the development of heart failure." (PMID 37234159, 2023). "For example, proscillaridin A, predominantly indicated for heart failure, has been empirically demonstrated to kill MYC-overexpressing LSCs in both T-ALL and AML models, potentially through downregulating acetylation of MYC target genes." (PMID 36009388, 2022).
heart failure (continued). "Increasing studies have suggested elevated level of MYC in HCM, consequently promoting cardiomyopathy and heart failure." (PMID 34136543, 2021). "The study also indicates that the three CSA-signature genes (MYC, MAP2K1, and STAT3) may not only act as potential biomarkers for heart failure but also be potential targets for future research in the development of new treatment strategies for heart failure." (PMID 37234159, 2023). "In addition, stem-like genes such as CTNNB1, MYC, and HIF1A may also attenuate heart failure after cardiomyopathy." (PMID 40717095, 2025). "However, unlike heart failure, MYC, ESR1 and HIF-1 pathway have main functions in TAAD." (PMID 37283588, 2023).